KRAS (KRas proto-oncogene, GTPase)
Diseases named in the same sentence as KRAS in open-access papers (continued):
Sharing a sentence is not in itself a finding about the gene and the disease.
lung adenocarcinoma (continued). "Finally, the TCGA lung adenocarcinoma (LUAD) database was consulted to study the expression of ACE2 in EGFR- and KRAS-mutant samples and ACE2 expression was correlated with EGFR/HER, RAS, BRAF, ROS1, ALK, and MET mRNA expression." (PMID 36077610, 2022). "We found a novel gene, ZNF24, which upregulated SLC7A5 protein expression rather than mRNA expression in KRAS mutant lung adenocarcinoma." (PMID 36505791, 2022). "It has been identified that most of the driver gene alterations in lung adenocarcinoma in never-smokers include EGFR, KRAS mutations, and so on." (PMID 35991047, 2022). "Our case study highlights two cases of KRAS-mutant (KRAS G12C) lung adenocarcinoma patients that have never been reported before in the Arabian Gulf." (PMID 36004014, 2022). "This has created a great surge in demand for treatments for this cancer, but the lack of cases concerning KRAS-mutant lung adenocarcinoma in MENA has been a major setback preventing us from learning more about effective treatment plans." (PMID 36004014, 2022). "ZNF24 promoted the growth of KRAS mutant lung adenocarcinoma by upregulating SLC7A5 protein expression, which suggested that ZNF24 is a new biomarker of KRAS mutant tumors and could be a new potential therapeutic target for Ras-driven tumors." (PMID 36505791, 2022). "Mutations in the KRAS gene have been associated with poor prognosis for lung adenocarcinomas, but implications of the loss of heterozygosity (LOH) of KRAS have not been investigated." (PMID 35574381, 2022). "All ERBB2 mutated patients were diagnosed with lung adenocarcinoma, were never smokers, and wild‐type for EGFR, KRAS, and ALK hotspot alterations." (PMID 36251951, 2022). "KRAS is one of the most common oncogenic drivers in lung adenocarcinoma (LUAC) and a great molecular diversity as well as phenotypic heterogeneity has been found in KRAS-mutant LUACs which could be interpreted by the co-occurring genetic events." (PMID 33777757, 2021). "Finally, we validated the in vitro results in KRAS‐mutant patient‐derived xenograft (PDX) and a genetically engineered mouse model (GEMM) of KrasG12D‐induced lung adenocarcinoma that precisely recapitulates the human disease." (PMID 34369083, 2021). "However, based on our molecular mechanism that explains K-Ras targeting, we included in our cellular analysis KRAS mutant, HIF-1α high, and/or Gal3 high cancer types, such as pancreatic and lung adenocarcinoma." (PMID 33672199, 2021). "For this, we selected the A549 human lung adenocarcinoma cell line for transfection since this line overexpresses an oncogenic KRas mutant (G12S) but expresses no endogenous RASSF5, thus allowing us to introduce our engineered mutants on a null background." (PMID 34717958, 2021). "Activated mutant KRAS could promote the expression of SCL7A11, thus inhibiting ferroptosis in lung adenocarcinoma." (PMID 34277151, 2021). "In our study, we found that SDPR expression was not only decreased in KRAS-mutant NSCLC cells, and KRAS-driven murine tumor from GEMMs, but also downregulated in human NSCLC specimens based on GEO datasets, TCGA datasets, and lung adenocarcinoma tissue array." (PMID 33435990, 2021). "Different copy number profiles in lung adenocarcinoma tumors with and without mutations in EGFR or KRAS have been described, but information about structural events have not been included in these studies." (PMID 34625038, 2021). "Based on the analysis of RNA-sequencing data, we identified a fusion transcript of CD63–BCAR4 in a Korean patient with lung adenocarcinoma who did not harbour any known activating mutations in EGFR and KRAS genes." (PMID 33204025, 2021).
lung adenocarcinoma (continued). "Now, we are screening some lung adenocarcinoma cell lines harboring gene mutations, such as EGFR mutations, ALK rearrangement, KRAS mutations, and BRAF mutation, and other cell lines without gene mutations to detect MTAP gene and protein expression." (PMID 31965001, 2020). "195/469 (41.6%) patients had triple-negative (EGFR-negative/KRAS-negative/ALK-negative) lung adenocarcinomas." (PMID 30744664, 2019). "This study was aimed at investigating the prognostic significance of Baculoviral IAP repeat containing 5 (BIRC5) in lung adenocarcinoma (LAD) lacking EGFR, KRAS, and ALK mutations (triple-negative (TN) adenocarcinomas)." (PMID 31093306, 2019). "NanoFEN and chemotherapy treatment significantly inhibited tumor progression in lung squamous carcinoma xenografts, lung adenocarcinoma xenografts (b left) and CRC xenografts, the latter with or without mutated KRAS (d left)." (PMID 31332161, 2019). "The patient did not harbor any activating mutation of EGFR, KRAS, or ALK genes; he was diagnosed as poorly differentiated lung adenocarcinoma stage 2B at the age of 51 and was a light smoker that used one pack per year." (PMID 31083279, 2019). "From these results, we analyzed publicly available data to investigate whether sortilin expression could be affected by oncogenic drivers such as KRAS or EGFR amplification, as observed in lung adenocarcinoma." (PMID 29084952, 2017). "In KRAS-mutant lung adenocarcinoma, in particular, strategies to inhibit the KRAS protein directly have not produced consistent results." (PMID 28030802, 2017). "We present the first portrait of clinically actionable alterations in lung adenocarcinoma of Indian origin that includes EGFR, KRAS, EML4-ALK, AKT1, PIK3CA, FGFR4 and ERBB2, similar to that identified in other ethnic groups, and an additional subset of patients with FGFR3 mutations." (PMID 27998968, 2017). "We also found KRAS-mediated up-regulation of PD-L1 induced the apoptosis of CD3+ T cells and mediated immune escape in lung adenocarcinoma cells, which could be reversed by anti-PD-1 antibody or ERK inhibitor treatment." (PMID 28451792, 2017). "In this study, we selected 3 lung adenocarcinoma cell lines SPC-A1, SCH-1153 and A549, which were all inappropriate for TKIs due to the lack of EGFR mutations/ALK-fusions or possessing KRAS mutations." (PMID 29285248, 2017). "Lungs from non-vaccinated mice were fully covered with lung adenocarcinoma, whereas lungs from KRAS-specific peptide vaccinated mice appeared virtually free of gross tumors." (PMID 29137294, 2017). "In addition, our data showed that ectopic expression of RMRP promoted theexpression of KRAS, FMNL2 and SOX9 in lung adenocarcinoma cell." (PMID 27906963, 2016). "Two KRAS-mutant lung adenocarcinoma cell lines, SK-LU-1 and NCI-H23, did not express PD-L1 at both mRNA and protein levels." (PMID 27846317, 2016). "KRAS mutation was described as a negative prognostic marker for OS and DFS in lung adenocarcinoma more early in 1990." (PMID 26840022, 2016). "We did not observe any activation of NF-κb in human KRAS-mutant lung adenocarcinomas; in fact, NF-κb activation was significantly lower in KRAS-mutant tumors compared to other Raf/MAPK mutant tumors." (PMID 27301828, 2016). "LY294002, a PI3K inhibitor, did not decrease PD-L1 expression in any of the three KRAS-mutant lung adenocarcinoma cell lines (upper)." (PMID 27846317, 2016). "We presented the results of the EGFR, KRAS and ALK mutational analyses in patients with lung adenocarcinomas in a prospective study, regardless of clinical stage." (PMID 27655296, 2016).
lung adenocarcinoma (continued). "To confirm and further explore this conclusion, we directly induced the expression of mutant KRAS or mutant EGFR in established lines of human lung adenocarcinoma cells known to be driven by either mutant EGFR (PC9 cells; in-frame deletion in exon 19) or by mutant KRAS (H358 cells; G12C)." (PMID 26047463, 2015). "Using anti-mutant KRAS-siRNA, and siGLO-green as our model siRNAs, we hoped to verify the involvement of NTSR1 in the internalization of siRNA-loaded hybrid nanoparticles in A549 and H23 lung adenocarcinoma cell lines." (PMID 26410728, 2015). "In a recent study of lung adenocarcinomas, mutation rates for EGFR (39%), KRAS (4%), ALK (15%), and HER2 (5%) in never-smoker groups differed from rates in current or former smoker groups (10%, 35%, 4%, and 1%, respectively)." (PMID 25760072, 2015). "Unlike lung adenocarcinoma, pulmonary LELC rarely presents with EGFR mutations, KRAS mutations or ALK rearrangements." (PMID 26361045, 2015). "Human lung adenocarcinomas (LUAD) contain mutations in EGFR in ∼15% of cases and in KRAS in ∼30%, yet no individual adenocarcinoma appears to carry activating mutations in both genes, a finding we have confirmed by re-analysis of data from over 600 LUAD." (PMID 26047463, 2015). "In lung adenocarcinomas, EGFR mutation was higher in female and non-smoking patients, KRAS mutation only in patients with wild-type EGFR gene was higher." (PMID 26582224, 2015). "EGFR/KRAS/ALK-negative lung adenocarcinoma in never-smokers is highly heterogeneous at the somatic mutation level." (PMID 24576404, 2014). "Although genome-scale characterization of lung adenocarcinoma has been performed, a comprehensive somatic mutation analysis of EGFR/KRAS/ALK-negative lung adenocarcinoma in never-smokers has not been conducted." (PMID 24576404, 2014). "We screened 230 surgically resected lung adenocarcinoma samples to identify EGFR/KRAS/ALK-negative tumors in never-smokers." (PMID 24576404, 2014). "NTRK-1 fusions have been identified in 3 of 91 lung adenocarcinoma samples that were EGFR/KRAS/ALK-1/ROS-1 negative." (PMID 25505733, 2014). "The genomic makeup of EGFR/KRAS/ALK-negative lung adenocarcinomas in never-smokers is remarkably diverse." (PMID 24576404, 2014). "In our previous study, we reported that 90% of 52 lung adenocarcinoma samples from East Asian never smokers harbored driver mutations in just EGFR, KRAS, HER2 and ALK genes." (PMID 24533074, 2014). "The frequency of EGFR, KRAS, HER2 mutations and EML4-ALK fusion were 75.3%, 2%, 5.9% and 5%, separately, in recent analysis of 202 lung adenocarcinoma samples from Chinese patients who never smoked." (PMID 24533074, 2014). "In contrast, ectopic expression of DOK2 in KRAS-mutant A549 lung adenocarcinoma cells did not suppress tumor growth or activation of RAS." (PMID 24255704, 2013). "On the other hand, targeted treatments for mutant KRAS-driven lung adenocarcinoma and lung squamous cell carcinoma have not been developed other than chemotherapy that target both cancer cells and normal proliferating cells." (PMID 23976985, 2013). "In lung adenocarcinoma KRAS mutations are associated with poor prognosis and non-responsiveness to EGFR inhibitors whereas KRAS wild-type tumors with EGFR mutations are linked to better prognosis and response to EGFR inhibitors." (PMID 24280411, 2013). "Except for KRAS, all oncogenic drivers can be effectively targeted in clinic, highlighting the importance of molecular classification of lung adenocarcinoma in never smokers." (PMID 22140546, 2011). "In our previous study, approximately 90% of lung adenocarcinomas from never smokers harbor known oncogenic mutations in just 4 genes of EGFR, KRAS, HER2, EML4-ALK." (PMID 22140546, 2011).
lung adenocarcinoma (continued). "Additional significant interaction was identified between KRAS and Protein Tyrosine Phosphatase Receptor Type D (PTPRD), RNA-Binding Motif Protein 10 (RBM10), and Neurogenic locus notch homolog protein (NOTCH1/2/3), reflecting novel immune-related mechanisms in KRAS-mutant lung adenocarcinomas." (PMID 40723270, 2025). "Therefore, we provide data on trends in OS of unselected patients with stage IV lung adenocarcinoma and EGFR or KRAS mutation, or no-mutation in a current and historic real-world population." (PMID 40227775, 2025). "The KRAS p.G12C mutations harbor more aggressive clinicopathologic and genomic features than other KRAS-mutant tumors and were associated with worse DFS after the complete resection of stage I–III lung adenocarcinoma, a correlation that was not investigated in our cohort." (PMID 40075579, 2025). "Accordingly, we addressed tumor heterogeneity by investigating cells harboring major mutations that are commonly found in lung adenocarcinoma, utilizing H1975 (EGFR L858R and T790M), PF901 (BRAF V600E), PF139 (KRAS G12C), and H838 (triple wild type with no known driver mutation) cell lines." (PMID 39227650, 2024). "However, these trials do not specifically enroll patients with KRAS-mutant lung adenocarcinoma, which our data suggest would most benefit from such a combination." (PMID 38635884, 2024). "Furthermore, KRAS and HIF1A-As2 were highly expressed in the lung adenocarcinoma (LUAD) and lung squamous cell carcinoma (LUSC) compared to the normal lung from TCGA datasets, elevated in late-stage compared to early-stage tumors from a second independent cohort of Biomax LUAD paired TMA samples." (PMID 37041291, 2023). "Interestingly, suppression of PD-L1 in combination with docetaxel failed to enhance an anti-tumor response in a KRAS-mutant lung adenocarcinoma mouse model." (PMID 36874015, 2023). "However, despite the widespread availability of KRAS and/or EGFR mutation testing, these genetic abnormalities have been discovered in a subset of resected lung adenocarcinomas and not in squamous carcinomas." (PMID 35454856, 2022). "In addition, mutations in other genes like KRAS, BRAF or HER2 have been reported to be negative prognostic biomarkers in patients with lung adenocarcinoma, making the prognostic landscape more complex." (PMID 35012520, 2022). "Interestingly, we did not observe any significant association between specific KRAS amino acid mutational changes and RAG, suggesting that specific mutations do not drive RAS activity heterogeneity in distinct ways in the context of lung adenocarcinoma." (PMID 36163168, 2022). "In pre-clinical testing, sotorasib was found to impair cell viability in pancreatic and lung adenocarcinoma cell lines, in monolayer and spheroid models, with a high potency and high selectivity, as it had no impact on cell viability of non-KRAS G12C cell lines." (PMID 35251972, 2022). "Given the early promise of finally targeting KRAS indirectly through this approach, there was a randomised controlled trial, the SELECT-1 trial, which compared docetaxel alone to a combination with selumetinib, a MEK inhibitor in patients with KRAS-mutant lung adenocarcinoma." (PMID 34064232, 2021). "The frequency of CD63–BCAR4 in lung adenocarcinoma without EGFR and KRAS mutations could be estimated as approximately 3% based on the present study (1/29) and Wang’s study (1/33); however, it might be much lower in Caucasians and/or in smokers." (PMID 33204025, 2021). "Furthermore, two patients with stage IV lung adenocarcinoma detected with EGFR exon 19 deletion and either concurrent KRAS K117N (n = 1) or concurrent de novo EGFR T790M (n = 1) achieved partial response with A+T regimen, with PFS of > 16.0 months and 10.3 months, respectively." (PMID 34663309, 2021).
lung adenocarcinoma (continued). "We also suggest that lung adenocarcinomas harbouring BCAR4 fusions might be a clinically relevant subgroup with a targetable oncogenic driver, among patients without EGFR and KRAS mutations." (PMID 33204025, 2021). "In human lung adenocarcinoma, IKKα has been shown to be highly expressed and it has been demonstrated that a heat shock protein 90 (HSP90) inhibitor blocks IKK function and has superior efficacy against KRAS-mutant lung adenocarcinoma compared with a specific IKKb inhibitor." (PMID 35582445, 2020). "In addition, we did not investigate the mutations of KRAS and ALK genes in EGFR-wt patients, which play a major role in the progression of lung adenocarcinoma and are mutually exclusive from EGFR gene mutations." (PMID 29383112, 2017). "Oncogenic mutations in KRAS are found in about 25% of lung adenocarcinomas, however many tumors with mutations in KRAS are no longer “dependent” on K-ras for survival, thus targeting these tumors will depend on understanding the molecular underpinnings of K-ras dependence." (PMID 26918447, 2016). "We demonstrate here that 24% of advanced lung adenocarcinoma express high levels of mesothelin, and that high mesothelin expression is associated with EGFR wild-type and mutant KRAS and, independent of the mutation status, is associated with decreased overall survival." (PMID 26028668, 2015). "We extended study of epigenetic priming to a patient-derived xenograft (PDX) model of lung adenocarcinoma, LX7, which has poorly differentiated histology, is negative for KRAS, EGFR (exons 18–21), and BRAF mutations, and is negative for ALK-fusions by cytogenetic analysis." (PMID 25474141, 2015). "However, these profiles did not segregate by histology (lung adenocarcinoma-appendiceal cancer (KRAS G12D and GNAS R201C), and lung adenocarcinoma-liposarcoma (CDK4 and MDM2 amplification pairs))." (PMID 26418953, 2015). "Validated cancer drivers such as ERRBB2, EGFR, and KRAS demonstrated high copy number versus mRNA expression correlation in the corresponding cancer types they regulate (ERBB2 r = 0.9 in breast cancer, EGFR r = 0.8 in lung adenocarcinoma, KRAS r = 0.9 in ovarian cancer)." (PMID 24874471, 2014). "However, there is no molecularly targeted therapy for mutant KRAS-driven lung adenocarcinoma, the most frequent type of lung adenocarcinoma in the Caucasian population." (PMID 23976985, 2013). "Furthermore, a large gene set derived from microarrays well stratified lung adenocarcinomas in one ALK-mutated and two EGFR/KRAS/ALK-mutation negative subgroups." (PMID 27605195, 2013). "Here we explore this hypothesis by investigating the mutational frequency of genes with known or expected functions in host-immune interactions in two cohorts of lung adenocarcinoma patients in the TCGA database, mutant KRAS (n = 163) and no known driver (WT) (n = 313)." (PMID 36092893, 2022). "We apply this “evolutionary triage” principle to TCGA data from EGFR-mutant, KRAS-mutant, and NEK (non-EGFR/KRAS) lung adenocarcinomas." (PMID 36612014, 2022). "Lung adenocarcinoma subtypes 1–2 had the highest number of focal amplifications containing potential oncogenes (ERBB2, FGFR1, KRAS, MET), whereas LUAD-3 contained none." (PMID 33888829, 2021). "In this study, we aimed to perform CGP on tumor specimens from patients with lung adenocarcinomas who tested negative for EGFR, KRAS and ALK previously at our institution." (PMID 26992220, 2016).